EGFR (epidermal growth factor receptor)
Diseases named in the same sentence as EGFR in open-access papers (continued):
Sharing a sentence is not in itself a finding about the gene and the disease.
renal carcinoma (78 papers, 2004 to 2025). A carcinoma arising from the epithelium of the renal parenchyma or the renal pelvis. "Our data show that EGFR loss leads to resistance to apoptosis induced by rhTRAIL (50ng/ml) in renal cancer cells." (PMID 32413049, 2020). "Our results show that EGFR loss leads to the resistance of renal cancer cells to cisplatin, HDAC inhibitors and TRAIL." (PMID 32413049, 2020). "Although EGFR loss leads to cell survival and multiple drug resistance, sunitinib can further inhibit renal cancer cell proliferation upon loss of EGFR." (PMID 32413049, 2020). "In this study, three SNPs (rs11238349, rs6954351, and rs7796139) from intron 1 of EGFR and identified through our initial screen were statistically significantly associated with risk of renal cancer." (PMID 19603096, 2009). "We show that EGFR loss inhibits renal cancer cell proliferation." (PMID 32413049, 2020). "Cooperative signaling between MET and EGFR has been observed during kidney development, and aberrant cross-signalling in renal cancer noted to have major implications for therapy." (PMID 38703764, 2024). "It has been reported that low concentration glucose (500 mg/l) can up-regulate PD-L1 expression by over-activating the downstream ERK pathway through up-regulating EGFR expression in renal cancer cells." (PMID 37434177, 2023). "The enhanced phosphorylation of EGFR, MET, and EPHA2/B1 upon FLCN loss is interesting in light of previous studies that linked these kinases to renal cancer." (PMID 35863698, 2022). "Especially CD106 (VCAM1) and EGFR seem promising immunotherapeutic targets that show higher surface expression levels in the context of renal cancer." (PMID 36221114, 2022). "In renal carcinoma cells, sunitinib induces EMT which has been linked to sunitinib resistance via EGFR activation." (PMID 35066605, 2022). "This mixed information, with some reports showing lack of activity, and others signs of potential benefit, decreased the interest of pharmaceutical sponsors to promote the development of anti-EGFR strategies for renal cancer." (PMID 34399807, 2021). "As glucose metabolism can regulate the expression of EGFR, and the mutation and expression of EGFR can regulate the expression of PD-L132, we hypothesised that PD-L1 expression is regulated by activating EGFR in the context of glucose deficiency in renal cancer cells." (PMID 33462221, 2021). "Previous studies have demonstrated that the expression of PD-L1 was upregulated in renal cancer cells in glutamine deprivation culture medium via the EGFR/ERK/C-Jun pathway." (PMID 34573287, 2021). "mTOR has significant cross-talk with the Ras pathway, which is hyperactive in renal cancer cells, possibly through the induction of receptor tyrosine kinases (like, c-Met, EGFR (Epidermal Growth Factor Receptor) etc.)." (PMID 32635337, 2020). "We also evaluated the inhibitory effects of multiple inhibitors as well as alterations in PI3K/AKT and RAS/RAF/MEK/ERK downstream pathways in the EGFRwt/wt and EGFR-/- renal cancer cells." (PMID 32413049, 2020). "EGFR was strongly expressed in all renal cancer cell lines, with percentages ranging from 59% to 88.9%." (PMID 29423418, 2017). "FACS was used to assess the surface expression of EGFR in a series of human renal cancer cell lines, including 786-O, ACHN, OSRC-2, and Ketr-3." (PMID 29423418, 2017). "For example, although the mechanism of action by which EGFR is activated in ELSTs from patients with VHL remains to be determined, loss of VHL increases levels of the EGFR ligand, TGF-α, and activates EGFR in renal cancer cells." (PMID 26027747, 2015). "Several small connected modules inside unstable transcription patterns can be usually observed and further examined as drug potential targets, such as the module in the WI-38 cancer module system or EGFR module in the renal cancer patient." (PMID 25405334, 2014).
renal carcinoma (continued). "The association with kidney carcinomas is novel in this analysis, but may be due to the fact that a number of urothelial carcinomas express Erbb2 (also known as Her2neu), which interacts with EGFR and may introduce genetic instability leading to high cancer maximum multiplicity in this analysis." (PMID 21714919, 2011). "PAR1 activation accounted for α-thrombin-induced tyrosine phospholyration of EGFR in renal carcinoma cells." (PMID 20723226, 2010). "Three regions containing genes associated with renal cancer were identified: caspase 1/5/4/12(CASP 1/5/4/12), epidermal growth factor receptor (EGFR), and insulin-like growth factor binding protein-3 (IGFBP3)." (PMID 19603096, 2009). "There is strong evidence supporting the biological relevance of genetic variants in EGFR and IGFBP3 and renal cancer risk." (PMID 19603096, 2009). "We identified both haplotypes and SNPs in CASP1/5/4/12, EGFR, and IGFBP3 that were statistically significantly associated with risk of renal cancer." (PMID 19603096, 2009). "This is especially relevant to renal cancer, as both EGFR and SGLT1 are expressed in the kidney, where glucose uptake is important." (PMID 19603096, 2009). "In summary, the results from this study suggest that genetic polymorphisms and haplotypes within the CASP1, CASP5, EGFR, and IGFBP3 genes are associated with renal cancer risk." (PMID 19603096, 2009). "In the second EGFR region, variant haplotype TGA was associated with an increased risk of renal cancer compared to the common haplotype (OR: 1.32, 95% CI: 1.02–1.70)." (PMID 19603096, 2009). "In vitro studies demonstrated that EGFR-positive kidney carcinoma cells could be selectively identified and killed by CAR-NK-92 cells." (PMID 38694508, 2024). "Additionally, renal cancer cells exhibit increased PD-L1 expression when glutamine is deprived, mediated through the activation of EGFR/ERK/c-Jun signaling." (PMID 38594256, 2024). "Previous studies revealed that ST3GAL1 may account for sialylation of EGFR in renal cancer cells, while ST3GAL6 may promote sialylation of EGFR in HeLa cells." (PMID 36092699, 2022). "Down-regulation of EGFR or TGFα using RNAi or their pharmacological targeting with blocking antibodies resulted in inhibition of the proliferation of in vitro cellular models of renal cancer." (PMID 34399807, 2021). "Therefore, glucose metabolism can regulate the expression of PD-L1 through the EGFR/ERK/c-Jun pathway in renal cancer, and elevated PD-L1 can also regulate glycolysis by improving the expression of PFKFB3." (PMID 33462221, 2021). "The dysfunction of EGFR had been reported in many kinds of cancers 22-24, including renal cancer." (PMID 33531995, 2021). "Therefore, high expression of PD-L1 in renal cancer is mediated by glycolysis through activation of the EGFR/ERK/c-Jun pathway." (PMID 33462221, 2021). "In conclusion, knockout of overexpressed EGFR dramatically inhibits renal cancer cell growth." (PMID 32413049, 2020). "For instance, EGFR enhances the development of renal cancer." (PMID 32795273, 2020). "Receptor tyrosine kinases, such as VEGFR, PDGFR and EGFR, play important roles in renal cancer." (PMID 32413049, 2020). "Additionally, the cytotoxicity of CAR-NK-92 cells against EGFR+ renal cancer cells was positively correlated with the E/T ratios." (PMID 29423418, 2017). "We next investigated if the ability of the dI (F4) or dIII (A5) specific IgGs to block signaling correlated with the ability to inhibit growth of a panel of ERBB2-positive breast (BT-474 & SK-BR-3) and gastric (NCI-N87) cells as well as the EGFR-positive renal cancer cell line (ACHN)." (PMID 25386657, 2014). "In renal carcinoma cells, the matrix metalloproteinase (MMP) inhibitor GM 6001 diminishes the tyrosine phosphorylation of the EGFR induced by PAR1, pointing to a critical involvement of metalloproteinase activity in the PAR1-mediated transactivation of the EGFR in renal carcinoma cells." (PMID 24215724, 2013).
renal carcinoma (continued). "Thus, the aim of the present study was to analyze protein expression of EGFR by immunohistochemistry and to investigate the role of EGFR gene copy number changes in relation to EGFR overexpression in this type of renal cancer." (PMID 22475688, 2012). "In addition, with a haplotype-based sliding window method, we identified the same genes with regions that were associated with renal cancer risk at a FDR level <10%: CASP1/5/4/12, EGFR, IGFBP3, and VCAM1." (PMID 19603096, 2009). "In conclusion, our evaluation has identified common genetic variants in CASP1, CASP5, EGFR, and IGFBP3 that could be associated with renal cancer risk." (PMID 19603096, 2009). "It is hypothesized that aspartame may influence the migratory behavior of renal cancer cells by modulating the PAR1/EGFR-related pathway, thereby providing a foundation for elucidating the molecular mechanisms underlying KIRP and for the development of potential therapeutic targets." (PMID 41515956, 2025). "Consequently, blocking the EGFR has been reported to inhibit angiogenesis in renal cancer in vivo." (PMID 38158791, 2024). "The EGFR/ERK/c-Jun pathway could regulate PD-L1 expression in renal carcinoma." (PMID 37420173, 2023). "Similarly, silencing of EGFR decreases VHL-dependent renal cancer growth." (PMID 26027747, 2015). "Treatment with EGFR inhibitor also induced PD-L1 expression and ERK1/2 phosphorylation in renal cancer cells." (PMID 38459595, 2024). "Decreases in the expression of EGFR and PI3K/Akt signaling result in delayed entry of cancer cells into S and G2/M phases, which ultimately reduces the proliferation of renal carcinoma cells." (PMID 37838167, 2023). "In renal cancer cells, inhibition of OGT reduces expression of pro-proliferation and pro-survival protein EGF receptor (EGFR) as well as expression of its downstream targets PI3K/Akt." (PMID 37838167, 2023). "For EGFR, KICH and KIRP were compared against KIRC, since KIRC is the most frequent renal cancer subtype." (PMID 36221114, 2022). "And mechanism studies showed that MIAC inhibits the activation of the EREG/EGFR signaling pathway by direct binding to AQP2 protein, thereby inhibiting renal cancer progression and metastasis in vitro and in vivo." (PMID 36117171, 2022). "Reactome enrichment analysis demonstrated that YTHDC1 was negatively correlated with EGFR and FGFR signaling pathways in renal cancer cells, which are reported to be the major driver pathways for the tumorigenesis of renal cancer." (PMID 35974388, 2022). "This set of data provides further independent indications that VCAM1, EGFR and CD24 are highly expressed in renal cancers and that their high expression is a poor prognostic marker for survival." (PMID 36221114, 2022). "This indicates that MIAC directly binds to AQP2, and finally plays a role in inhibiting the occurrence and development of renal cancer by inhibiting the expression of EREG and EGFR and the activation of downstream signaling pathways." (PMID 36117171, 2022). "COMMD5/HCaRG overexpression inhibited tumor growth and angiogenesis in a homograft renal carcinoma mouse model by promoting de-phosphorylation of ErbB2/HER2, ErbB3/HER3, and EGFR, leading to inhibition of ErbB signaling pathways." (PMID 33768002, 2021). "MiR-196a promotes renal cancer cell migration by directly targeting Bram1 and inhibits Smad1/5/8 phosphorylation and MAPK pathways through BMPR1A and EGFR." (PMID 34803496, 2021). "The complementary transcript of EGFR, noted as EGFR-AS1, had drawn attention to the researchers to dig the deep relationship between EGFR and EGFR-AS1 in renal cancer." (PMID 33531995, 2021). "A biological link between EGFR expression and NFκB activation was described for different solid cancer types, like NSCLC, but also for renal cancer." (PMID 31323891, 2019). "Taken together, these data indicated that EGFR-specific CAR-NK-92 cells and cabozantinib have synergistic antitumor effects against EGFR-positive renal cancers." (PMID 29423418, 2017).
renal carcinoma (continued). "To further investigate the in vivo effect of the combination of EGFR-specific CAR-NK-92 cells and cabozantinib, we established another subcutaneous xenograft model in NOD/scid mice with human renal cancer ACHN cells expressing firefly luciferase (ACHN-Luc)." (PMID 29423418, 2017). "In kidney cancer cell lines, LPA-induced HB-EGF shedding and subsequent EGFR transactivation is mediated by ADAM10 in ACHN cells, whereas ADAM17 is responsible for these events in human renal carcinoma cells (CaKi2) and Human kidney carcinoma cell line (A498)." (PMID 25356505, 2014). "This study revealed for the first time the tumor suppressor potential of the lncRNA-encoded micropeptide MIAC in RCC, which inhibits the activation of the EREG/EGFR signaling pathway by direct binding to AQP2 protein, thereby inhibiting renal carcinoma progression and metastasis." (PMID 36117171, 2022). "Moreover, ACK1 stabilizes EGFR, and knockdown of ACK1 increases the sensitivity of renal carcinoma cells to gefitinib." (PMID 33495411, 2021). "Previous studies have shown that the down-regulation of acetyltransferase KAT3B induces apoptosis in renal carcinoma and the variations in the expression levels of MYSTI/MOF/KAT8 may affect the cell cycle and the EGFR signaling pathway." (PMID 34899851, 2021). "Similarly to SKOV3 cells, NRF2-silenced renal carcinoma A498 (shNRF2-A498) retained reduced levels of c-MET, EGFR, p-c-MET, p-EGFR, p-AKT, and p-ERK1/2 when compared to those of the A498 control cells." (PMID 29291022, 2017). "EGFR and IL6 are markers of highly invasive tumors, including renal carcinoma." (PMID 25405334, 2014). "After confirming CAR-NK expression, researchers went for in vitro analysis using human renal cancer cell lines 786-O, ACHN, and EGFR-negative colorectal cancer cell lines as control." (PMID 38694508, 2024).
chordoma (76 papers, 2010 to 2025). Chordomas are rare malignant tumors arising from embryonic remnants of the notochord in axial skeleton. "Taken together, our results suggest that of the chordoma-implicated genes we successfully tested in our assay, only overexpression or misexpression of the chordoma-implicated EGFR and KDR RTKs is sufficient to trigger the onset of notochord hyperplasia." (PMID 31221659, 2019). "In contrast, the chordoma-implicated receptor tyrosine kinases (RTKs) EGFR and Kdr/VEGFR2 are sufficient to transform notochord cells." (PMID 31221659, 2019). "By immunohistochemistry, the tumor was positive for brachyury, the molecular hallmark of chordoma, and showed weak–moderate membrane and cytoplasmic EGFR." (PMID 27200287, 2016). "Among the very few molecular dysregulations that have been associated with chordoma malignancy are the frequent dysregulations of the receptor tyrosine kinases (RTKs), EGFR, PDGFR and MET." (PMID 24621885, 2014). "Other signaling pathways distinctive of chordomas that have been targeted are those linked to the epidermal growth factor receptor (EGFR); inhibitor drugs, such as cetuximab, gefitinib, and erlotinib, have been used in a small number of patients." (PMID 23662285, 2013). "Gain of chromosome 7 is frequently reported in chordomas, and multiple genes that encode TK are located on chromosome 7, including the EGFR." (PMID 22613809, 2011). "Thus, loss of miR-608 or miR-34a could enhance chordoma malignancy by inducing overexpression of EGFR, MET and inhibiting apoptosis." (PMID 24621885, 2014). "Preclinical research has confirmed that EGFR signaling supports the growth and survival of chordoma cells, and that inhibition of this pathway can impair tumor growth both in vitro and in vivo models." (PMID 40943706, 2025). "The patient was switched to the EGFR tyrosine kinase inhibitor afatinib, which has demonstrated activity in chordomas." (PMID 41404256, 2025). "Although the activating mutations typically seen in other cancers, such as non-small cell lung cancer, are uncommon in chordoma, EGFR’s elevated expression and activation suggest it contributes to tumor development and progression." (PMID 40943706, 2025). "The results of our study compare favorably with previous studies that identified PDGFRB/PDGF, PI3K/AKT, RAS/MAPK, or EGFR as recurrently dysregulated pathways in chordomas." (PMID 40627883, 2025). "Among the molecular targets under investigation for chordoma, the Epidermal Growth Factor Receptor (EGFR) has also shown considerable promise." (PMID 40943706, 2025). "Advanced chordomas have been reported to overexpress receptor tyrosine kinases (RTKs), including epidermal growth factor receptor (EGFR) and activated platelet-derived growth factor receptor (PDGFRB)." (PMID 41228286, 2025). "In fact, a 2013 study has already demonstrated that erlotinib, a small molecule EGFR inhibitor, impeded the growth of a patient-derived chordoma in a xenograft model." (PMID 38741774, 2024). "Chordomas commonly activate pathways such as EGFR, PDGFβ, IGFR1, IGF1, mTOR, MET, and PI3K and involve chromatin remodeling genes such as ARID1A, PBRM1, and SETD2." (PMID 39193055, 2024). "EGFR inhibitors, identified as a potential therapeutic target for chordoma by screening 1097 focused libraries of compounds, and specific inhibitors that target EGFR and cyclin G-associated kinase (GAK) showed efficacy in chordoma cells." (PMID 37111759, 2023). "Anecdotal reports on the responsiveness of chordoma to epidermal growth factor receptor (EGFR) inhibitors are promising." (PMID 36768973, 2023). "Genes previously implicated in chordoma biology, including CDK6, SOX9, and EGFR, were also recovered." (PMID 37024492, 2023).